MTOR (mechanistic target of rapamycin kinase)
Diseases named in the same sentence as MTOR in open-access papers (continued):
Sharing a sentence is not in itself a finding about the gene and the disease.
tumor (continued). "The recent explosion in the number and diversity of PI3K/AKT/mTOR inhibitors in clinical development creates the need for a rational approach to identify the tumor/patient that will benefit the most from a specific inhibitor." (PMID 36901954, 2023). "Many tumor cells rely on leucine, methionine, glutamine, and arginine to regulate growth and promote survival through cellular pathways such as mTOR and PI3K." (PMID 36960210, 2023). "The PI3K/AKT/mTOR signaling pathway has emerged as a critical player in the regulation of tumor immune microenvironment (TME)." (PMID 37152048, 2023). "Although the PI3K/AKT/mTOR pathway is one of the most altered pathways in human tumours, therapies targeting this pathway have shown numerous adverse effects due to positive feedback paradoxically activating upstream signaling nodes." (PMID 37877351, 2023). "These nanocarriers extend mTOR inhibitor circulation by reducing clearance and preventing premature release, optimizing pharmacokinetics, increasing drug exposure, and enhancing tumor accumulation." (PMID 37834408, 2023). "RHBDD2-CKO-induced upregulation of CXCL12 in stromal cells leads to anticancer drug resistance via activating the PI3K-Akt-mTOR pathway in tumor cells." (PMID 37264057, 2023). "For instance, PI3K‐AKT and mTOR signaling pathways are critically involved in tumor invasion and metastasis." (PMID 38087815, 2023). "Cellular responses dominated by the PI3K/AKT/mTOR pathway are frequently seen in KIRC and are associated with tumor progression." (PMID 37379129, 2023). "Treatment with Everolimus, a mammalian target of rapamycin (mTOR) inhibitor, can improve the anti-tumor activity of lr-NK cells by upregulating TRAIL expression." (PMID 37239062, 2023). "The mTOR pathway plays a vital role in tumorigenesis by regulating metabolism and promoting tumor growth, making it a promising target for cancer therapy." (PMID 37564659, 2023). "We found that LINC01278 can induce autophagy to inhibit tumour progression by suppressing the mTOR signalling pathway." (PMID 36713034, 2023). "Based on the regulatory role of mTOR in cell biological behavior, it follows that mTOR plays an important role in tumorigenesis and tumor development." (PMID 37179344, 2023). "Next, we confirmed that DT2216 and AZD8055 led to a significant reduction in BCL-XL and MCL-1 levels, respectively, which was associated with significant inhibition of mTOR substrates (p-4EBP1 and p-S6) upon AZD8055 treatment in H1048 tumor lysates." (PMID 36588105, 2023). "A recent study also supports our discovery that p62 acted as a tumor suppressor in mice with persistent mTOR activation and defective autophagy." (PMID 37081115, 2023). "The lapatinib-treated tumor tissues showed reduced expression of p-mTOR, p-TSC2, and p-P70S6K in the TSC-NC and TSC2-WT groups." (PMID 37160904, 2023). "Our research showed that the vinorelbine arrests cells at the mitotic phase, induces apoptosis, and normalizes tumor blood vessels but upregulates survivin and activates the mTOR/p70S6K/4EBP1 pathway." (PMID 38203186, 2023). "The mammalian target of rapamycin (mTOR) is a serine/ threonine protein kinase that regulates tumor growth, proliferation, metabolism, cell growth, and immunity." (PMID 37631344, 2023). "Activation of different signaling cascades such as JAK2/STAT3, NF-κB, PI3K/AKT/mTOR, and Wnt/β-catenin pathways through the tumor microenvironment leads to upregulation of antiapoptotic proteins." (PMID 36986514, 2023). "Further studies are warranted for determining the in vivo anti-tumor effects of salidroside as a pure compound and as an inhibitor of mTOR signaling." (PMID 37370698, 2023). "An increase in mTOR signaling was shown to promote tumor growth and progression, making it a viable anticancer target possibly used in the anticancer activity of metformin." (PMID 37180606, 2023). "In the PI3K/AKT/mTOR pathway, AKT activation facilitates tumor invasion and metastasis by phosphorylating mTOR." (PMID 37953768, 2023).
tumor (continued). "The deregulation of PI3K/AKT/mTOR signaling is responsible for tumor initiation, chemo-resistance and poor prognosis in CRC." (PMID 36835075, 2023). "KDM4A promotes HIF1α expression by inhibiting histone methylation in the HIF1α promoter region, thereby upregulating DDIT4 expression and activating the mTOR signaling pathway to promote tumor proliferation, migration, and invasion." (PMID 36611207, 2023). "NAT1 can exert anti-tumor activity by inhibiting the phosphorylation of pi3k/Akt/mTOR signaling pathway." (PMID 37626132, 2023). "This concept is strongly supported by transcriptomics of mTOR-driven tumors influencing endothelial cell function and tumor angiogenesis." (PMID 37874650, 2023). "PDAC patient tissues showed a significantly higher levels of p-AKT, p-ERK, and p-mTOR in PDAC cancerous tissue compared to their surrounding non-tumor tissues." (PMID 37503215, 2023). "In the IHC analysis, the groups treated with Tumor+100 mg/kg melatonin were compared when the mTOR signaling pathway and factor 8 (F8) expression were compared with the control group." (PMID 38188676, 2023). "Within this nanomedicine, the tumor matrix-targeting peptide palmitic-K(palmitic)CREKA can self-assemble into a nano-micelle to encapsulate Rapamycin (mTOR inhibitor) and SBC-115076 (PCSK9 inhibitor)." (PMID 37896137, 2023). "FBXW7 is a main tumor suppressor due to its ability to control proteasome-mediated degradation of several oncoproteins such as c-Jun, c-Myc, Cyclin E1, mTOR, and Notch1-IC." (PMID 36934104, 2023). "IND, through phosphorylating P-S6K, restores the mTOR pathway, regulating the tumor microenvironment (TME), ultimately stimulating CD8+ T cell development for tumor immunotherapy." (PMID 38139233, 2023). "It was found that the high-stem risk score group was significantly enriched in classical tumor pathways such as WNT, TGF-β, JAK-STAT3, mTOR, etc.." (PMID 37717019, 2023). "Penicillixanthone A exhibited potent cytotoxic activity against both Hep G2 and A549 tumour cells, and it regulated the expression of the PI3k-Akt-mTOR signalling pathway." (PMID 38067576, 2023). "And then, ZIC2 transcriptase-positively regulates UBE2C and activates AKT/mTOR signaling pathway to promote tumor malignant progression." (PMID 37496990, 2023). "In BC, the PI3K/AKT/mTOR pathway leads to cell growth and tumor proliferation and is involved in endocrine resistance." (PMID 37175800, 2023). "Aberrancies in mTOR can influence tumor growth in many ways, from promotion of anabolism to evasion from natural killer (NK) cell immunosurveillance." (PMID 37465112, 2023). "In GBM, neurofibromin, the NF1 gene product, negatively regulates mTOR signaling through downregulation of the Ras/MAPK pathway, hyperactivation of mTOR, and increased cell proliferation, favoring tumor progression." (PMID 36831117, 2023). "The tumor microenvironment is characterized by elevated glucose levels that activate various genes, such as mTOR." (PMID 37841922, 2023). "This compound reduces tumor cell proliferation and induces apoptosis and autophagy through the phosphorylation inhibition of mTOR." (PMID 36839989, 2023). "The efficacy of PI3K/mTOR inhibitors against TFE3-fusion RCC cell lines confirms the importance of the mTOR pathway as a driver of tumor cell growth." (PMID 37095531, 2023). "The mammalian target of rapamycin (mTOR) signaling in CSCs promotes the infiltration and aggregation of MDSCs at tumor sites." (PMID 36810098, 2023). "Leucine is an mTOR pathway agonist that upregulates the mTOR protein expression, thereby activating the mTOR signaling pathway and promoting tumor growth." (PMID 37660174, 2023). "EA specifically interferes with several signaling cascades, including PI3K/AKT, NF‐B, CDK6, TGF‐/Smad3, and AKT/mTOR, to perform its anti‐tumor actions." (PMID 38107139, 2023).
tumor (continued). "In another study, the intratumoral injection of cholesterol-conjugated miR-99a, which targets mTOR, led to a reduction in tumor mass in xenograft mice bearing HCC." (PMID 37631344, 2023). "PI3K/AKT/mTOR, as one of the classical tumors signaling pathways, has been shown to regulate both apoptosis and autophagy to exert anti-tumor effects." (PMID 36864518, 2023). "CD98hc-NRG1 fusion promotes the proliferation, invasion, migration, and tumor growth of lung cancer cells via the upregulation of PI3K/AKT/mTOR and FAK-Src pathways." (PMID 37823053, 2023). "In melanoma and in ovarian cancer cells, PD-L1 stimulates tumor cell proliferation and alters autophagy through the regulation of mTOR, in addition to promoting the generation of tumor-initiating cells driven by mTORC1." (PMID 37834467, 2023). "PI3K/AKT/mTOR signaling pathway promotes the proliferation, differentiation and migration of tumor cells." (PMID 37900137, 2023). "Within the hypoxic tumor microenvironment, the activated AKT/mTOR pathway causes lipogenesis and lipid accumulation during HCC progression and leads to proliferation, increased viability, and angiogenesis." (PMID 36768977, 2023). "Our findings identify that CTSG has a tumor-inhibiting effect on CRC cells via controlling the activity of the Akt/mTOR/Bcl2 mediated anti-apoptotic signaling pathway." (PMID 37151875, 2023). "Tuberous sclerosis complex (TSC) is a rare genetic multisystem disorder caused by loss-of-function mutations in the tumour suppressors TSC1/TSC2, both of which are negative regulators of the mammalian target of rapamycin (mTOR) kinase." (PMID 37108467, 2023). "In RMS cells, mTOR inhibition can successfully abrogate tumor growth with a reduction in proliferation and invasiveness, as well as an induction of apoptosis through inhibition of BCL-2 expression." (PMID 37958442, 2023). "Intracellular acidification mediated by the V-ATPase is important for a wide array of processes that can enhance tumor growth including receptor mediated endocytosis, autophagy, mTOR signalling, and β-Catenin signalling." (PMID 37463144, 2023). "Our findings indicate that LINC01278 functions as a tumour suppressor by inhibiting the mTOR signalling pathway to induce autophagy." (PMID 36713034, 2023). "CDK4/6 inhibitors can promote anti-tumor immunity by increasing the production of type III interferons and tumor antigen presentation and suppressing regulatory T cells, through reducing the activity of E2F and mTOR inhibitors are immunosuppressive." (PMID 37264081, 2023). "This showed that the AMPK/mTOR signaling pathway is an effective target for SFB for exerting anti-tumor effects through the autophagic pathway." (PMID 37175435, 2023). "mTOR is a crucial factor that participated in the various solid malignant tumours’ progression, and application of inhibitor of mTOR to delay tumour progression has become a promising strategy." (PMID 36750558, 2023). "The mTOR signaling pathway is crucial for the growth of tumors, so inhibiting mTOR can play an anti-tumor role." (PMID 38264667, 2023). "Both silencing of FASN and treatment with FASN inhibitor inactivated the mTOR pathway, supporting a tumor suppressor role of FABP5 via inhibition of mTOR through FASN." (PMID 37416772, 2023). "In general, PEComa tumours display inappropriate activation of the mammalian target of rapamycin (mTOR) pathway." (PMID 37504306, 2023). "Innate PD-L1 signaling in tumor cells regulates mTOR, autophagy, growth, metastasis, drug resistance (e.g., to small molecules, chemotherapy, immunotherapy), epithelial to mesenchymal transition, and DNA damage repair in various types of tumor cells." (PMID 37006252, 2023). "It is worth noting that TOP2A was not only positively correlated with PI3K / AKT/ mTOR tumor signal pathway but also correlated with metastasis-related EMT, MMP protein, angiogenesis, and the Hippo-YAP pathway." (PMID 37980167, 2023).
tumor (continued). "This leads to the disinhibition of the PIP3/Akt/mTOR pathway and, ultimately, the development of cancer and the resistance of the tumour to treatment, and blocking PTEN leads to seizures." (PMID 38067243, 2023). "GAS5 is downregulated in tumor cells; however, its overexpression can inhibit tumor cell proliferation and migration by inactivating the mTOR pathway." (PMID 37371481, 2023). "Low TSC2 expression leads to hyperactivation of the mTOR pathway and promotes tumor energy metabolism." (PMID 37256211, 2023). "Expression levels of WNT-1 and mTOR were analyzed in the plasma membrane, cytoplasm, and nucleus of the tumor cells, and tumor grade was evaluated using H&E staining." (PMID 37176048, 2023). "These tumors show responses to mechanistic target of rapamycin (mTOR) inhibition with everolimus in regards of tumor growth and seizure control, and thus everolimus has been approved by FDA and EMA." (PMID 36566461, 2023). "The mechanism of action of these drugs is based on the inhibition of the energy generation pathways of the tumor cell: glycolysis, the mTOR pathway, and DNA synthesis." (PMID 37223676, 2023). "We showed the correlation of ZNRF2 expression levels with MTOR in some tumours, such as DLBC, KIRP, LGG, SKCM, THYM and UVM (p < 0.001)." (PMID 37551845, 2023). "The AKT/mTOR pathway is well-known that plays a significant role in regulating tumor metabolic homeostasis, including the Warburg effect, which ultimately facilitates the growth and spread of cancerous cells." (PMID 37365670, 2023). "The PI3K/mTOR signaling pathway has been documented to promote tumor cell progression by targeting the pyruvate dehydrogenase complex and reprogramming the morphology and function of mitochondria." (PMID 37949877, 2023). "PTEN is a tumor suppressor that regulates the PI3K/AKT/mTOR pathway important in senescence and apoptosis." (PMID 37169941, 2023). "Some studies have confirmed that long noncoding RNAs (lncRNA) can promote tumor metastasis via PGK1-activated AKT/mTOR pathway." (PMID 37524857, 2023). "It specifically binds to the C-terminal FRB region of mTOR, prevents mTOR from modifying downstream target proteins, and inhibits the proliferation and growth of tumor cells by participating in the regulation of various substances metabolism." (PMID 37601696, 2023). "When the meta-analysis was carried out, it became evident that anthocyanins target the Akt/mTOR pathway to reduce tumor cell growth, migration, and invasion processes." (PMID 37190229, 2023). "PF-04691502 is another dual PI3K/mTOR inhibitor that can repress tumor growth and progression through the induction of apoptosis." (PMID 37046703, 2023). "We observed that the mTOR pathway was activated in tumour samples using immunohistochemical analyses of p-mTOR and p-S6k; metabolome analysis showed that the BCAAs accumulated in tumours." (PMID 37076565, 2023). "They found that inhibiting the AKT/mTOR signaling pathway by blocking tumor PD-L1 can reduce expression of glycolysis enzymes, suggesting there is an important role for PD-L1 in tumor glucose utilization." (PMID 36980323, 2023). "The interaction between PI3K/AKT/mTOR signaling and metabolism demonstrates the close connection between the oncogenic signaling network and tumor metabolism." (PMID 36768977, 2023). "Once PI3K/Akt/mTOR is activated, the proliferation and invasion of tumor cells will be out of control." (PMID 36768602, 2023). "Previous studies have shown that PI3K/AKT/mTOR signaling pathway plays a key role in the signal transduction, apoptosis, proliferation, cell cycle and growth of tumor cells." (PMID 36609277, 2023).
tumor (continued). "Using a targeted capture of 557 genes involved in DNA damage response and PI3K/AKT/mTOR pathways, we conducted next-generation sequencing of DNA from matched blood and tumor tissue from 71 HGSC participants." (PMID 37460928, 2023). "The phosphoinositide 3 kinase (PI3K)/AKT/mechanistic Target Of Rapamycin (mTOR) pathway promotes cell growth, cell survival, proliferation, and tumor growth." (PMID 37298315, 2023). "The first evidence has also been obtained that GCs repress mTOR signaling, for instance in tumor cells and regulatory T cells." (PMID 36766792, 2023). "We functionally evaluated the essentiality of mTOR complex components in the mouse KEP tumor–derived KEP1.23 and KEP2.E3 cell lines overexpressing either GFP or murine Myc." (PMID 37642941, 2023). "The aim of this study was to explore the effect of XIN-10, a dual PI3K/mTOR inhibitor, on the growth as well as antiproliferation of tumor cells and to investigate the anti-tumor mechanism of XIN-10 by further exploration." (PMID 37834269, 2023). "We found this subset up-regulated PD-1 in the presence of tumor-derived lactate and PD-1 upregulation significantly down-regulated the mammalian target of rapamycin (mTOR)-mediated proliferation of this subset within the TME." (PMID 37098069, 2023). "The IGF-1/AKT/mTOR pathway is also one of the key targets for ES treatment and IGF receptor 1 (IGF-1R) and mTOR inhibitors prevent tumour growth and improve ES survival rate in a mouse xenograft model." (PMID 37895198, 2023). "The pathway induces tumor growth in two ways: 1) mTOR is a vital regulator of the initiation step of autophagy, and its activation inhibits autophagy; 2) activated AKT inhibits caspase 3 and 9 by phosphorylating Ser196, ultimately inhibiting apoptosis." (PMID 37370314, 2023). "mTOR is typically increased in malignancies, such as HCC, and is linked to a poor prognosis, poor tumor differentiation, and early recurrence." (PMID 36937390, 2023). "Data have pointed to the fact that the inhibition of mTOR in CSCs is an effective way to control tumour propagation via the reduction of CSCs and stemness removal." (PMID 37156724, 2023). "With regard to the mTOR localization patterns, the percentage of tumor cells exhibiting nuclear localization of mTOR increased as the tumor grade increased, whereas mTOR expression in the cytoplasm and plasma membrane decreased with tumor grade." (PMID 37176048, 2023). "In tumor cells, it has been demonstrated that the mTOR pathway is responsible for stimulating tumorigenesis, inducing the expression of inhibitory molecules, such as programmed cell death ligand-1 (PDL-1), and suppressing anticancer immune responses." (PMID 37046703, 2023). "For example, miR-218, as a tumor suppressor, is downregulated in oral cancer targeting the mTOR signaling pathway." (PMID 37161350, 2023). "A known pathway for the induction of CXCL12-mediated anticancer drug resistance is the activation of the PI3K-Akt-mTOR system in tumor cells." (PMID 37264057, 2023). "Everolimus (RAD001) is an oral analog of rapamycin that inhibits proliferation and induces apoptosis and autophagy of tumor cells through indirectly blocked mTOR." (PMID 37169756, 2023). "Torin2 is an ATP-competitive mTOR inhibitor of the quinoline class, which inhibits phosphorylation of both mTORC1 and mTORC2 and was shown to exhibit anti-tumor effects in several types of tumors." (PMID 37240419, 2023). "It has been reported that gene therapy targeting HER-2 promotes tumor cell apoptosis and restrains tumor cell invasion as well as tumor angiogenesis via blocking the PI3K/AKT/mTOR pathway." (PMID 36967718, 2023). "Among those, PI3K/AKT/mTOR pathway is a critical pro-survival signalling pathway, that modulates cell growth, proliferation, apoptosis and survival in tumor cells." (PMID 37025487, 2023).